MMP9 (matrix metallopeptidase 9)
Diseases named in the same sentence as MMP9 in open-access papers (continued):
Sharing a sentence is not in itself a finding about the gene and the disease.
bladder cancer (continued). "For instance, circ-0001361 was recently found to be highly expressed in bladder cancer, and it could directly interact with miR-491-5p to elevate MMP9, thereby promoting bladder cancer invasion and metastasis." (PMID 32867570, 2020). "Furthermore, nimbolide impaired the migration and invasion of bladder cancer cells by reducing MMP-9 expression, which was mediated by transcriptional suppression of the transcription factors NF-κB, AP-1, and Sp-1." (PMID 31391858, 2019). "CXCL8 and MMP9 overexpression correlates with the poor prognosis of bladder cancer." (PMID 31681401, 2019). "Therefore, MMP-9 is amenable to therapeutic intervention by synthetic and natural inhibitors of bladder cancer; this provides perspectives for future studies." (PMID 31391858, 2019). "In this study, we examined the molecular signaling cascades of nimbolide-induced suppression of proliferation, migration, and invasion of bladder cancer EJ cells by conducting an inclusive analysis of signaling pathway, cell cycle modulation, and transcription factor-controlled MMP-9 regulation." (PMID 31391858, 2019). "Maspin acts as an HDAC1 inhibitor, which may modulate the p21, cyclin D1, MMP9, and vimentin expressions in bladder carcinoma cells." (PMID 31861435, 2019). "EPO gene could induce ERK1/2 phosphorylation and increase MMP-9 expression in both bladder cancer cells and vascular smooth muscle cells." (PMID 30915348, 2019). "Additionally, MMP-9 protein, which is a key factor of bladder cancer invasion, is regulated by the PI3K/Akt signaling pathway." (PMID 31228937, 2019). "In bladder cancer, CXCL5 was found to be significantly upregulated and the CXCL5/CXCR2 axis could promote the migration and invasion of bladder cancer cells by activating the PI3K/AKT-induced upregulation of MMP2/MMP9." (PMID 29743818, 2018). "For example, MMP-9 plays an important role in apoptosis and cell migration, while Wnt signaling plays an important role in cell proliferation, cell cycle regulation, apoptosis, and migration in bladder cancer." (PMID 30103466, 2018). "However, there has been a report that a mixture of lysin, proline, arginine, ascorbic acid, and GTEs inhibited cancer cell invasion via the regulation of MMP-2 and MMP-9 production in a bladder cancer cell line (T24)." (PMID 30103466, 2018). "Another study conducted by the same group of scientists revealed that MAG treatment of 5637 bladder cancer cells inhibits expression of MMP-9 induced by Tumor necrosis factor–alpha (TNF-α) by decreasing the binding affinity of the transcription factor NF-κB to the MMP-9 promoter." (PMID 30103472, 2018). "Because MMP-9 is one of the key factors by which bladder cancer cells acquire the capacity to metastasize and invade adjacent tissues or distant organs, the inhibitory activity of hydrangenol against MMP-9 might be particularly valuable." (PMID 30034317, 2018). "MMP9 may therefore serve as a favorable biomarker and its overexpression may predict better outcomes in bladder cancer patients." (PMID 28427222, 2017). "Our results are consistent with this hypothesis, and we found that knockdown of lncRNA-UCA1 in hypoxic exosomes increased E-cadherin expression, while decreasing the expression levels of vimentin and MMP9 in bladder cancer cells or xenograft tumor tissues." (PMID 28841829, 2017). "Consistent with the results of the wound healing and Boyden chamber assays, inhibition of MMP-9 indicated that DATS might impede the metastatic potential of bladder cancer cells." (PMID 28680385, 2017). "Futhermore, the secretion of MMP9 protein was increased in invasive bladder cancers." (PMID 27317771, 2016). "In fact, a significant body of literature has described MMP9 to be upregulated in bladder cancer." (PMID 27317771, 2016). "Furthermore, the MMP9 expression level was drastically reduced in GOLPH3-silenced cells compared with control cells accompanied by significantly increased levels of MMP9 in bladder cancer tissues compared with ANT." (PMID 26375441, 2015).
bladder cancer (continued). "To explore whether MMP-2 and MMP-9 are involved in regulation of human bladder cancer cell invasion, we first compared their expression levels between T24 and T24T cells." (PMID 25402510, 2015). "There was a variation in the level of MMP9 between the patients in different stages of bladder cancer compared to control; at stages T1and T2, this variation was not significant neither in schistosomal bladder cancer (0.544 ng/ml) nor in non-schistosomal bladder cancer patients (0.446 ng/ml)." (PMID 25135219, 2014). "Reduced protein levels of both NGAL and MMP-9 have been detected in urine samples from bladder cancer patients with clinical relapse suggesting that reduced levels of these proteins may be used as indicators of tumor progression." (PMID 24742531, 2014). "So in conclusion, measurements of urinary levels of MMP3 and MMP9 may aid in the diagnosis of both schistosomal and non schistosomal bladder cancer at different stages." (PMID 25135219, 2014). "We confirmed that MMP2 and MMP9 were frequently up-regulated in bladder cancer tissues." (PMID 24180482, 2013). "We next measured the level of MMP-2 and MMP-9 in this two bladder cancer cells." (PMID 24314030, 2013). "In addition, low sensitivity of urinary MMP-9 was detected in bladder cancer, which was approximately 40% in two independent studies including our study (62%), showing a limited diagnostic value of MMP-9 in the urine of such type of malignancy." (PMID 23672427, 2013). "ROCK1, MMP2, MMP9 were up-regulated in bladder cancer tissues." (PMID 24180482, 2013). "Moreover, IL-8 blocking antibody is able to down-regulate MMP-9 expression and activity in orthotopic bladder cancer xenografts." (PMID 23349885, 2013). "In human bladder cancer cells, TNF-alpha could stimulate the secretion of matrix metalloproteinase-9 (MMP9) which has been implicated in tumor invasion and metastasis." (PMID 22811589, 2012). "Among the genes and proteins examined, we observed that IL-5, IL-20, IL-28A, and their receptors produced by bladder cancer cells induced migration, invasion, transcription factor-mediated MMP-9 expression, and activation of signaling pathways, such as the MAPK and Jak-Stat pathways." (PMID 22962576, 2012). "Thus, MMP-9 has an important effect on the progression of bladder cancer." (PMID 41273852, 2025). "Correlation analysis in bladder cancer samples from TCGA BLCA demonstrated a positive correlation between mRNA levels of IGF2BP3 and SNAI1 (Snail), SNAI2 (Slug), CDH2 (N-cadherin), VIM (vimentin), and MMP9, further supporting the association between IGF2BP3 and EMT-related markers." (PMID 38504159, 2024). "Therefore, MMP9 protein was decreased in human bladder cancer T24 cells, which might be due to β-catenin reduction." (PMID 35563650, 2022). "Similarly, the researchers attenuated the proliferation and migration of bladder cancer cells through GPNMB gene knockout while reducing the expression of MMP-2, MMP-9, and β-catenin and demonstrated that high GPNMB expression is a risk factor for bladder cancer." (PMID 36090016, 2022). "Thus, our data suggest that MSSV could impair the migration and invasion abilities of bladder cancer cells by suppressing transcription factor-mediated expression of MMP-9." (PMID 33430488, 2021). "Moreover, CM derived from TAM-like PBM-derived CXCL8 could contribute to MMP-9 expression in bladder cancer cells, suggesting that it is also involved in bladder cancer invasion and metastasis." (PMID 32201645, 2020). "In contrast, MMP-9 showed a significant elevation in advanced stages only of both schistosomal and non schistosomal bladder cancer patients (10.33, 21.22 ng/ml) compared to control (0.409 ng/ml) and this elevation of both markers was much higher in non schistosomal bladder cancer." (PMID 25135219, 2014).
bladder cancer (continued). "In the present study, the authors investigated the effect of blocking the MMP-9 expression by genome editing using the CRISPR/Cas9 technique on the migration and invasion capabilities of human T24-Luc bladder cancer cells." (PMID 41273852, 2025). "In a study utilizing bladder cancer cell lines, CD46 overexpression enhanced the upregulation of MMP9 to trigger phosphorylation of p38 MAPK and PKB and to promote increased activity of activator protein 1 (AP-1) activity via c-Jun." (PMID 40309774, 2025). "For example, the infiltration of TAMs in the tumor microenvironment leads to the increase in CXCL8, which in turn promotes bladder cancer cells to secrete MMP-9, VEGF, and E-cadherin, enhancing the migration and angiogenic capacity of bladder cancer cells." (PMID 40131539, 2025). "Melatonin inhibits bladder cancer cell migration and invasion by downregulating ZNF746-regulated MMP-9/MMP-2 signaling." (PMID 40756978, 2025). "In bladder cancer patients’ samples, IL-1β is highly expressed and induces the urokinase-type plasminogen activator receptor and MMP9 expression by activating the MAPK and NF-κB pathways, thus promoting bladder cancer cell invasion." (PMID 39858071, 2025). "Recent studies suggest that TANs can secrete MMP9 and VEGFA, contributing to lymphatic vessel formation and LN metastasis in cancers such as bladder cancer." (PMID 40739091, 2025). "The present study demonstrated that inhibiting MMP-9 expression using the CRISPR-Cas9 genome editing technique is feasible and can successfully impair T24 bladder cancer cell migration and invasion capacities in vitro." (PMID 41273852, 2025). "Recent studies have shown that the infiltration of TANs increases the levels of VEGFA and MMP9 via the ERK/JNK pathway, facilitating lymphangiogenesis in bladder cancer." (PMID 40083688, 2025). "TAM-derived CXCL8 promotes MMP-9, VEGF, and E-cadherin expression in bladder cancer cells and enhances bladder cancer cell migration, invasion, and angiogenesis." (PMID 39199574, 2024). "The downregulation of NANOG decreased bladder cancer cell migration and invasion as well as MMP2 and MMP9 mRNA levels." (PMID 37627900, 2023). "In human bladder cancer cells, suppression of MMP-2, MMP-9 and IL-6 expression, as well as induction of mesenchymal-to-epithelial transition (MET were found in the presence of DEX." (PMID 36980530, 2023). "Collectively, these findings suggest that SFN suppresses bladder cancer metastasis via the COX-2/MMP2, MMP9/ZEB1, and Snail pathway as well as the miR-200c/ZEB1 pathway." (PMID 37627900, 2023). "A similar effect was observed for SW780 bladder cancer cells, where EGCG down-regulated the expression of NF-κB and MMP-9 and triggered the apoptosis of cancer cells." (PMID 37446908, 2023). "Another study found that melatonin inhibited the human bladder cancer cell lines HT1376, HT1197, RT4, and T24 by reducing cell proliferation, invasion, and migration through the suppression of the AKT/MMP9 pathway by decreasing ZNF746 protein expression." (PMID 37086261, 2023). "In this study, the bladder cancer tissues were examined to demonstrate the presence and activity of two gelatinases, MMP-2 and MMP-9." (PMID 36979935, 2023). "COL6A3 silencing suppresses the expression of MMP-2, MMP-9, and vimentin, then participates in the process of inhibiting EMT of bladder cancer cells." (PMID 35774273, 2022). "Focal adhesive complex, MMP2, MMP9, and angiogenic-related proteins were decreased, while FXR was overexpressed in bladder cancer cells." (PMID 35563650, 2022). "Capsaicin markedly inhibited cell migration through the suppression of SIRT1 deacetylase via proteasome-mediated protein degradation, thereby elevating β-catenin acetylation and decreasing MMP-9 and MMP-2 activation in T24 bladder cancer cells." (PMID 33996570, 2021).
bladder cancer (continued). "Studies have reported that TNF-alpha induced MMP-9 expression in bladder cancer cells by activating the transcription factor NF-kappaB, which is involved in the p38 MAP kinase-mediated control of MMP-9 regulation." (PMID 34868913, 2021). "In vitro study confirmed that urinary bladder cancer HT1376 cells were, via increased secretion of MMP-9, stimulated by TNF-α." (PMID 33923108, 2021). "CCL21/CCR7 enhanced bladder cancer cell proliferation and facilitated migration and invasion by increasing levels of MMP-2 and MMP-9." (PMID 33146700, 2020). "The infiltration of TAMs in the tumour microenvironment leads to the elevation of CXCL8, which in turn promotes the secretion of MMP-9, VEGF, and E-cadherin by bladder cancer cells." (PMID 32201645, 2020). "The association of SOD2 with aggressive metastatic cancer phenotype is further supported by positive correlation of increased SOD2 expression with consequent H2O2-related MMP9 and VEGF mRNA synthesis in bladder cancer." (PMID 29478325, 2019). "It was demonstrated that loss of miRNA-141 and miRNA-200b expression increases the invasion and migration capacities of bladder cancer cell lines and up regulates MMP-2, MMP-9, vimentin, N-cadherin while down regulates E-cadherin expression." (PMID 30544619, 2018). "MMP-9 dimer and MMP-9 monomer were multivariable predictors for distinguishing between patients with prostate and bladder cancer (P< 0.001 for each)." (PMID 30197761, 2018). "Corticosterone and prednisone were also shown to reduce the expression levels of MMP-9, IL-6, and VEGF genes in bladder cancer cells." (PMID 30518063, 2018). "As a result of inducing transactivation or transrepression of GR by dexamethasone, up-regulation of FKPB51 and GILZ or down-regulation of NF-κB and AP-1 as well as MMP-2, MMP-9, IL-6, and VEGF, respectively, has been documented in bladder cancer cells." (PMID 30518063, 2018). "Recent data indicate that p38 MAPK-driven MAPKAPK2 regulates the invasion of bladder cancer by modulating MMP-2 and MMP-9 activities." (PMID 28678918, 2017). "Using MMP-2/9 antibodies and ERK inhibitor PD98059, we validate that Derlin-1 induces bladder cancer invasion through activation of ERK signaling, which in turn upregulates MMP-2 and MMP-9 protein expression." (PMID 28178653, 2017). "As proof of concept, Jin and co-workers have recently shown that knockdown of HSP70 led to reduction of matrix metalloproteinase 9 (MMP9) mRNA expression and WASF3/Wave3 protein levels in bladder cancer (BC) cell line." (PMID 29311994, 2017). "It has been shown that when mast cells are co‐cultured with bladder cancer cells, CCL2 expression is elevated (after ERβ decrease) and EMT is activated in cancer cells, which express MMP‐9 and display enhanced invasive properties." (PMID 28599100, 2017). "Taken together, our findings elucidate a novel role of miR-199a-5p in the suppression of cell metastasis through regulation MMP-9 and EMT-related genes by targeting CCR7 in bladder cancer." (PMID 27814720, 2016). "Zymographic analysis of the expression levels of MMP-9 and active MMP-2 demonstrated a proportional increase with tumor grade and invasiveness in bladder cancer." (PMID 25621068, 2015). "qRT-PCR analysis found the expression of NF-κB-targeted genes, including CCND1, Bcl-2, MMP9 and VEGF were upregulated once overexpression of URGCP/URG4, whereas knockdown of URGCP/URG4 significantly inhibited the levels of these genes in bladder cancer cells." (PMID 26429874, 2015). "The p38 MAPK was activated during the log phase growth of bladder cancer cells and regulated invasion of bladder cancer by modulation of MMP-2 and MMP-9 expression and activity." (PMID 26312564, 2015). "Other studies have shown that IL–20 upregulated invasion-related genes like MMP–9 and MMP–12, which degrade extracellular matrix in breast and bladder cancers." (PMID 26440411, 2015).
bladder cancer (continued). "ROC curves generated from ELISA were used for measuring the accuracy of both MMP9 and MMP3 at different stages of bladder cancer." (PMID 25135219, 2014). "MMP-2 and MMP-9 were highly expressed in bladder cancer metastasis, so the NDRG2 likely inhibited the metastasis of bladder cancer by regulating the expression of MMP-2 and MMP-9." (PMID 24146910, 2013). "Increased expressions of VEGF and MMP-9 are reported to correlate with EMT change and poor prognosis of bladder cancer." (PMID 23637926, 2013). "Taken together, our study detected many species of gelatinases in the urine of bladder cancer patients with primary tumor (both bilharzial and non bilharzial) including MMP-2, MMP-9, MMP-9 dimer, MMP-9/NGAL, MMP-9/TIMP-1 and ADAMTS-7." (PMID 23672427, 2013). "In recent, p38 is implicating mediating bladder cancer invasion via regulation of MMP-2 and MMP-9 at the level of mRNA stability." (PMID 22454661, 2012). "Urinary MMP-9 levels, serum MMP-7 levels, and tissue levels of MMP-2, MMP-7, and MMP-14 have been identified as prognostic markers of bladder cancer." (PMID 22852097, 2012). "Our findings are consistent with a study reported on human bladder cancer cells, where treatment with varying concentrations of NaHS (exogenous H2S donor) led to a significant increase in the expression levels of MMP-2 and MMP-9, along with enhanced invasion capacity." (PMID 41583211, 2025). "In a previous study, non-metastatic bladder cancer cells transfected with IL-8 exhibited increased MMP-9 expression and invasive potential." (PMID 41273852, 2025). "This study specifically utilized RT4 cells, a well-characterized, non-invasive bladder cancer model, to investigate the impact of proTAME, cisplatin, and gemcitabine on MMP2/MMP9-mediated migration, establishing a foundation for subsequent research using more aggressive bladder cancer models." (PMID 40136519, 2025). "Another cohort study reported that upregulated urinary Eubacterium abundance alters extracellular matrix protein 1 (ECM1) in bladder tissue, enhancing matrix metalloproteinase 9 (MMP9) expression via the ERK1/2 phosphorylation pathway, ultimately facilitating bladder cancer progression." (PMID 40708946, 2025). "In human bladder cancer cells, genistein suppresses production or release of angiogenic proteins of PDGF-A, tissue factor (TF), and VEGF165, as well as enzymes involved in matrix degradation for MMP-2, MMP-9, and uPA." (PMID 38611849, 2024). "Moreover, MMP2, MMP9, MMP12, and MMP16-enriched KEGG pathways include “Bladder cancer, endocrine resistance, and relaxin signaling pathway”, etc.." (PMID 38560573, 2024). "Additionally, COL6A1 has been shown to inhibit bladder cancer invasion by down-regulating the activities of matrix metalloproteinases 2 (MMP-2) and MMP-9." (PMID 38339238, 2024). "Moreover, MMP9, MMP12, MMP14, and MMP16-enriched KEGG pathways include “Bladder cancer, endocrine resistance, and relaxin signaling pathway” etc.." (PMID 39493455, 2024). "In T24 human bladder carcinoma cells, CCL21 activation of CCR7 promoted cell proliferation and migration mediated by increased levels of matrix metalloproteinases 2 and 9 (MMP-2 and MMP-9)." (PMID 35203305, 2022). "After uncovering that over-expression of LINC00478 impaired the MMP9 expression in bladder cancer cells, we focused our efforts on investigating whether LINC00478 affects the bladder cancer cell malignant phenotype by modulating the expression of MMP9." (PMID 35504875, 2022). "Therefore, we suggest that scabertopin can downregulate the expression of MMP-9 by inhibiting the activation of the FAK/PI3K/Akt signaling axis and, ultimately, inhibit the invasiveness of bladder cancer cells." (PMID 36497458, 2022). "Similarly, another microRNA, miR-1275, also elevated CCR7, leading to a more aggressive cancer cell phenotype; and, in bladder cancer, decreased miR-199a-5p led to increased CCR7 and increased MMP-9 and elevated cell migration." (PMID 35203305, 2022).